LGR5 (leucine rich repeat containing G protein-coupled receptor 5)
Diseases named in the same sentence as LGR5 in open-access papers (continued):
Sharing a sentence is not in itself a finding about the gene and the disease.
cancer (continued). "We found higher levels of epithelial stem cell/cancer stem cell markers (e.g., Lgr5, Axin2, Cd44, Prom1/CD133) in the tumoroids derived from ApcMin/+ WT as compared with ApcMin/+ Stat2−/− mice." (PMID 38001683, 2023). "LGR5 exerts as a stem cell factor and promotes the maintenance of cancer stem cells, self-renewal, and stem cell proliferation by activation of downstream Wnt/β-catenin-signaling cascade." (PMID 36740668, 2023). "Dysregulated WNT signaling fosters the conversion of cancer cells toward a less differentiated phenotype reminiscent of LGR5+ stem cells that reside in intestinal crypts." (PMID 37309673, 2023). "Our study further defines a role for TCF7L1 in cancer stem cell biology by demonstrating that TCF7L1 mediates repression of LGR5 expression and that this contributes to reduction of spheroid formation efficiency." (PMID 36833408, 2023). "LGR5 has been serially described as a WNT target gene as well as a marker for (cancer) stem cells in multiple neoplasms." (PMID 37770230, 2023). "The cancer stem cell population in CRC is thought to have arisen from a mutated ISC population, and that LGR5 and SOX9 are ISC markers that reside in the crypt base columnar cells of the tissue." (PMID 37950151, 2023). "LGR5+ stem cells, like cancer cells, fail to express HNF4G and BTNL molecules, making crypt regions and tumors immune privileged sites, devoid of γδIELs." (PMID 37309673, 2023). "Recent studies have also implied that inhibitors of RSPOs or their receptors (such as LGR5) are being evaluated as candidate targets for cancer therapeutic intervention, which provides a valuable framework for developing new therapeutic strategies." (PMID 36645115, 2023). "Cell ablation experiments in xenografted human cancers with the specific cancer stem cell marker, LGR5, implied that the plasticity of non-cancer stem cells is regulated differently by the tumor microenvironment in the primary and metastatic sites." (PMID 37367867, 2023). "This suggests a possible role of LGR5 as a potential marker for cancer stem cells in colorectal carcinogenesis." (PMID 37512045, 2023). "Pioneering work by de Sauvage and colleagues revealed that Lgr5+ cancer stem cells are dispensable for primary CRC growth yet necessary for metastasis formation in experimental models." (PMID 36352230, 2022). "The mutation of apc that occurs in LGR5+ intestinal stem cells allows them to be transformed into cancer stem cells, and LGR5+ CSCs play a critical role in the development of CRCs via producing the heterogeneity of tumors." (PMID 36354674, 2022). "Thbs1 is expressed by Lgr5+ cancer stem cells in vivo and induces YAP activation in neighbouring epithelial cells." (PMID 35543624, 2022). "Stem cell plasticity underpins intestinal regeneration, and it is evident that Lgr5 cannot be used as a sole marker for putative cancer stem cell populations in established lesions." (PMID 35931031, 2022). "Recellularization of both decellularized tissues with CCAOs resulted in upregulation of different cancer stem cell populations, as determined by LGR5 and CD133, and an increased epithelial phenotype in dLN." (PMID 36741736, 2022). "Treatment with 100 mg/kg corylin in the AOM/DSS mice led to significantly decreased cancer stem cell and intestinal epithelial cell proliferation, including LGR5, CD44, Ki67, PCNA, BrdU, and Cyclin D1 levels, compared with the AOM/DSS group." (PMID 35269806, 2022). "Recent studies demonstrated LGR5 positive cells to make up a subpopulation of cancer stem cells (CSCs), proving the dual role of LGR5 to regulate "stemness" in both healthy ISCs and CSCs." (PMID 35154991, 2022). "Although it plays important regulatory effects in stem cells, LGR5 is highly expressed in both normal stem cells and CSCs, which makes it difficult to distinguish between normal stem cells and CSCs in cancer-targeted therapy." (PMID 36372898, 2022).
cancer (continued). "We observed significantly reduced proliferation rates in cancer cells transfected with LGR5 compared to those transfected with a control plasmid." (PMID 35778589, 2022). "In many cancer cells, the number of filopodia is increased, and LGR5+ intestinal stem cells form long cytonemes." (PMID 36040316, 2022). "The expression levels of CD44, Lgr5, and Nanog were high in MKN28 cells compared with those in MKN45 cells, suggesting that viperin expression in the cancer cell lines was associated with CSCs." (PMID 36227691, 2022). "LGR5 upregulation is observed in various cancers, including ISC-associated cancers, such as colorectal and stomach carcinoma, and this upregulation leads to the activation of the Canonical Wnt signaling pathway." (PMID 35154991, 2022). "Comparing LGR5 H-scores in carcinoma cells, LGSC and MC expressed much lower levels of LGR5 than other subtypes." (PMID 35778589, 2022). "Further, cells positive for pluripotency, stemness and cancer stem cell niche markers SOX2, ALDH1A1, EPCAM, LGR5 and PORCN were also significantly expanded in Ahr-deficient lesions along the time window analyzed." (PMID 34439225, 2021). "The team also observed Lgr5 expression in cancerous pancreas in the remaining islets and all ductal cancer cells." (PMID 34453639, 2021). "Lgr5+ cancer stem cells not only showed the typical stem cell signature, but also a reduction in cell-cycle-related signatures, supporting their potential function in chemotherapy resistance." (PMID 33671641, 2021). "Next, using cell line models, we found that the simultaneous suppression of HDGF and LGR5 synergistically disrupted the formation of cancer spheroids and downregulated the level of cancer stem cell markers." (PMID 34106558, 2021). "Upregulation of the upstream positive regulators for LGR5 have been reported to serve toward cancer progression." (PMID 34552611, 2021). "It has been demonstrated that LGR5-positive cancer cells functionally act as stem cells in human CRCs." (PMID 33732694, 2021). "The increasing expression pattern from normal tissue to cancer is a good indicator that the dominance of cells expressing LGR5 in the environment has increased." (PMID 34452555, 2021). "There also exist several studies that have examined the prognostic significance of LGR5 in BC, and mostly they show an immunohistochemical staining to detect LGR5+ cells in cancer tissues." (PMID 34493772, 2021). "Given that DCLK1 and LGR5 are markers of a reserve, stress-induced and active, cycling cancer stem cells, respectively, our future studies will focus on looking at the role of the pathway in differentially regulating these two stem cell populations." (PMID 34206989, 2021). "Several reports have indicated the role of LGR5 in cancer cell growth, metastasis, and sphere formation." (PMID 33827616, 2021). "We then performed qPCR analysis using total RNA isolated from the GFP- and RFP-enriched cells for cancer stem cell markers, LGR5, CD133, CD166, and OLFM4." (PMID 33946505, 2021). "On the other hand, LGR5 was found to be highly expressed in ES cells and in putative ES cancer stem cells and tumors that display a more aggressive phenotype, suggesting a role of LGR5 in ES tumorigenesis." (PMID 34771683, 2021). "PORCN is an acetyltransferase, important for maintaining the cancer stem cell niche, that participates in the secretion of proliferative factors that activate LGR5 such as, for example, Wnt." (PMID 34439225, 2021). "Lgr5-positive gastric cells expand during gastric tissue repair and metaplasia, and a subset of small intestinal Lgr5-positive cells co-expressing Dclk1 are described to behave as cancer stem cells." (PMID 33627749, 2021). "In CRC, hierarchical organization is maintained during disease progression, and functional cancer stem cells are marked by Lgr5 expression." (PMID 34572727, 2021).
cancer (continued). "Recently RNA in situ hybridization (ISH) techniques have been used to visualize LGR5 + cells in human tissues, and this has been proven to be successful in many types of cancers." (PMID 34493772, 2021). "Human LGR5 is a stem cell marker that acts as an oncogene in several human cancers, most notably in colorectal carcinoma." (PMID 34771683, 2021). "FOXL1, in turn, directly up-regulates Grem1 expression to antagonize BMP signaling and promote cancer progression by suppressing differentiation of Lgr5+ stem cells while inducing epithelial proliferation." (PMID 33197448, 2021). "CXCR4 has been shown to co-localize with CRC stem cell markers, such as Lgr5, CD133, and CD44, which are thought to be associated with the epithelial-mesenchymal transition process and resistance to cancer drug therapy." (PMID 35582377, 2021). "We also detected fusion events with genes known in the context of cancer such as LGR5-TSPAN8 in the low TIL group." (PMID 33980253, 2021). "On the other hand, in some cases, disruption in the LGR5 gene expression can induce drug resistance in a number of cancers." (PMID 33718760, 2021). "LGR5 is the preferred marker because it identifies immature cancer cells in a more specific way than the other two biomarkers." (PMID 35008827, 2021). "A complete explanation of this issue needs more research; nevertheless, our results suggest a different role of Lgr5 in cancer development." (PMID 32671503, 2020). "To test which cancer cells escape from the primary site, we filmed the behavior of Lgr5+ CSCs and Lgr5− cancer cells in vivo using multiphoton microscopy." (PMID 32169167, 2020). "Analysis of the migratory cells (i.e., cells that displaced more than half a cell diameter in 4 h) revealed that Lgr5+ CSCs and Lgr5− cancer cells mainly escaped as single cells and less frequently as cell clusters." (PMID 32169167, 2020). "Although the LRR-containing GPCR family member Lgr5/Gpr49 is reportedly responsible for the maintenance of intestinal stem cells and cancer stem cells, the biological function of Lgr4/Gpr48 is not yet fully understood." (PMID 32943626, 2020). "Previous studies on CRC showed that β-catenin is related to LGR5, a cancer stem cell marker, and that β-catenin induces expression of LGR5." (PMID 32293346, 2020). "Through interaction with its ligand R-spondin 2, Lgr5 functions as a negative regulator of Wnt-signaling to suppress the cancer proliferation and metastasis." (PMID 31901081, 2020). "Hits for the PF-NSC-like program included Wnt-signaling regulator LGR5 and the anti-apoptotic gene MCL1, as well as the cancer stemness-associated genes as potential druggable vulnerabilities." (PMID 32663469, 2020). "When we compared the expression levels of GLI1 and DCLK1 or LGR5 between matched pairs of normal and cancer tissues from CRC patients, we found that their expression levels were negatively correlated with MUCIN-2 expression in cancer tissue." (PMID 32814764, 2020). "Flow cytometry revealed expressions of normal stem cell markers (SSEA3, SSEA4, and LGR5) and cancer stem cell markers (CD24, CD44, CD117, ROR1, and CD133)." (PMID 32035490, 2020). "Despite its pivotal role in homeostasis, regeneration and cancer, little is known about the post‐translational regulation of LGR5." (PMID 31867777, 2020). "Combined this shows that the appearance of Lgr5+ CSCs is indispensable for the outgrowth of metastases founded by Lgr5− cancer cells." (PMID 32169167, 2020). "T-β-MCA, a known FXR antagonist, was reported to promote CRC progression in HFD-induced APCmin/+ mice through damaging DNA and increasing proliferation in leucine-rich repeat-containing G protein-coupled receptor 5 positive (LGR5+) cancer stem cells." (PMID 32486076, 2020). "Plasticity in human cancer cells can happen independently of SC-inducing factors, as Lgr5+ CSCs appeared in organoids that were seeded by Lgr5− cells and cultured in minimal CRC medium." (PMID 32169167, 2020).
cancer (continued). "A comparison of the gene signatures between normal mammary epithelial subpopulations and breast cancer subtypes implied that the claudin-low cancer subtype is remarkably similar to LGR5+Tspan8high MaSCs." (PMID 33234169, 2020). "The adult stem cell marker leucine-rich repeat-containing, G protein-coupled receptor 5 (Lgr5) has been shown to be involved in the properties of CSCs in cancer cell populations." (PMID 31935894, 2020). "Targeting cancer stem cells (CSCs) in the gut comes with the challenge that following ablation of LGR5+ CSCs, LGR5- cells have the potential to de-differentiate to CSCs." (PMID 33575256, 2020). "Next, we neutralized this plasticity by ablating newly formed Lgr5+ CSCs in early metastatic lesions and observed by intravital imaging that metastasis composed by only Lgr5− cancer cells stopped growing over time and ultimately regressed." (PMID 32169167, 2020). "Because growth of metastases seeded by Lgr5− cancer cells requires cells to become Lgr5+, we next addressed what is driving this plasticity." (PMID 32169167, 2020). "Monomethyl auristatin E (MMAE) is a tubulin-inhibiting cytotoxic drug that kills LGR5-positive cancer cells selectively." (PMID 33234169, 2020). "Clonogenic assays confirmed isolation of functional Lgr5+ CSCs, as these cells were twice as clonogenic as Lgr5− cancer cells." (PMID 32169167, 2020). "Next, we developed a flow cytometry strategy to isolate Lgr5+ CSCs and Lgr5− cancer cells from both organoids and primary tumors." (PMID 32169167, 2020). "Analysis of DT-treated CRC Lgr5eGFP organoids, in which Lgr5+ CSCs are selectively depleted, and post-sort confocal microscopy on untreated CRC Lgr5eGFP organoids confirmed that our gating strategy allowed to reliably isolate Lgr5+ and Lgr5− cancer cells." (PMID 32169167, 2020). "Consistently with the higher level of CD44, an established marker of stemness in OSCCs 24, UPCI-SCC-131 cells exhibited higher expression of the cancer stem cell marker, Lgr5 25-26 compared to HPV-positive UPCI-SCC-154 cells." (PMID 31929745, 2020). "The cancer stem-like cell marker Lgr5 and differentiation marker CK18 were detected using RT-PCR in HGC-27 and MGC-803 cells; TRAF6 knockdown resulted in the downregulation of Lgr5 and upregulation of CK18." (PMID 32724313, 2020). "In this study, a new analysis focusing on LGR5-positive carcinoma stem cells was performed to investigate differences in prognosis based on a carcinogenesis model of PD-CRC." (PMID 32293346, 2020). "Leucine-rich repeat-containing G-protein-coupled receptor 5 (LGR5) is a promising intestinal stem cell and carcinoma stem cell marker." (PMID 32293346, 2020). "All 29 cases contained carcinoma cells with some LGR5-positive dots, with a wide range of LGR5-positive cell staining." (PMID 32293346, 2020). "A recent report described differences in the presence of LGR5-positive carcinoma stem cells based on differences in MMR protein expression." (PMID 32293346, 2020). "First, we examined LGR-5 marker since it is correlated to the stemness and it was recently presented as a cancer stem cell marker for NB cells." (PMID 31638925, 2019). "Strikingly, Lgr5 has been referred to as a novel biomarker of various human cancers of the stomach, pancreas, liver, colon, and ovary during recent years." (PMID 31358061, 2019). "Further, the organoid-forming efficiency of whole cancer cells or Lgr5+ cells obtained from colon polyps of PKM2ΔLgr5-Tx mice was significantly increased when compared with PKM2ΔLgr5-Veh mice." (PMID 30996297, 2019). "Although previous studies have shown some therapeutic effects of Lgr5-targeted anti-cancer therapy, there still exist some safety issues due to the presence of Lgr5-expressing adult stem cells in adult mammals." (PMID 31358061, 2019). "It has been reported that stem cell/progenitor hierarchies are maintained in CRC tissue and that LGR5 is a cancer stem-cell marker." (PMID 31234887, 2019).
cancer (continued). "Lgr5 is overexpressed in gastrointestinal tumors and other types of cancer, compared to its relatively low expression in normal tissues." (PMID 31417548, 2019). "Leucine-rich repeat-containing G protein-coupled receptor 5 (Lgr5) has been recently discovered as a candidate marker of cancer stem cell populations." (PMID 31358061, 2019). "Further comprehensive studies investigating the plasticity of cancer cells and transitions between Lgr5− and Lgr5+ cancer cells are necessary." (PMID 31358061, 2019). "In contrast, PKM2-null cancer cells that originated from Lgr5-GFP+ cells in colon polyps of PKM2ΔLgr5-Tx mice expressed mainly PKM1." (PMID 30996297, 2019). "Lgr5 potentiates Wnt/β-catenin signaling pathway, thereby stimulating cancer stem cell proliferation and self-renewal." (PMID 31358061, 2019). "On the other hand, however, Lgr5-mediated suppression in canonical Wnt/β-catenin signaling has also been reported in certain cancers, such as B cell malignancies." (PMID 31358061, 2019). "Recently, it was reported that IL-1β regulates cell proliferation through stemness markers such as Bmi-1, Lgr-5, c-myc and Nanog in cancer stem cells." (PMID 31671670, 2019). "Lgr5+ stem cells in gastrointestinal organs play important roles in homeostasis, regeneration, and cancer development." (PMID 31212972, 2019). "Metformin performs an independent “Warburg effect” blockade to cancer progression and is able to reduce crypt stem cell markers expression such as LGR5+." (PMID 31339921, 2019). "Single targeting Lgr5+ CSCs in solid cancer through antibody-conjugated drug delivery system exhibited some anti-cancer therapeutic effects." (PMID 31358061, 2019). "In summary, we demonstrated that carcinogen-induced cancer arises from Lgr5+ crypt stem cells in Ppp2r1a−/− mice." (PMID 31905853, 2019). "Over recent years, Lgr5+ cancer SCs (CSCs) have emerged as fundamental drivers of intestinal tumorigenesis." (PMID 30389919, 2018). "Earlier studies have also suggested that LGR5 +cells had the propensity to become cancer stem cells with APC abnormalities." (PMID 30250044, 2018). "As expected, we noted an upregulation of cancer stem cell markers LGR5 and CD44, as well as epithelial-to-mesenchymal transition marker ZEB1, in the spheroids." (PMID 29463813, 2018). "Ectopic expression of NANOGP8 significantly up-regulates stemness transcription factors, EMT inducers, and cancer stem cell markers (CSC) including Lgr5." (PMID 29689047, 2018). "We observed that ectopic expression of NANOGP8 extremely up-regulates Lgr5 in cancer cells (>8 folds), and in turn, it significantly enhances translocation/accumulation of β-catenin in cancer cell nucleus." (PMID 29689047, 2018). "WNT signaling was found to be essential for the generation of cancer-initiating cells and two cancer stem cell markers—LGR5 and CD44—are known target genes of WNT signaling." (PMID 29652830, 2018). "For the MET-, IGFBP7, and LGR5 pathways targeted therapies have already been studied in other cancer types with varying results, however, the potential to target these biomarkers in EAC is yet to be investigated." (PMID 30185893, 2018). "LGR5 expression is elevated in a plethora of cancer types and contributes to cancer phenotype including invasion, migration, and tumorigenicity." (PMID 30089773, 2018). "GPCRs such as CXCR4, LPAR, PAR1, LGR5, and S1PR are up-regulated in many advanced cancers and induce invasion and metastasis, while CXCR4, CXCR1/2 and LGR5 have been linked to TIC-like phenotypes." (PMID 29255247, 2018). "It was reported that three bona fide markers for cancerous colon stem cells; CD44, Lgr5, and ALDH are highly expressed during the progression to carcinoma and are associated with shorter time to disease recurrence." (PMID 29343849, 2018). "This post-translational modification of Dvl3 in turn maintains LGR5 expression and enhances the cancer stemness properties in HCC." (PMID 28455968, 2017).